SOX9 (SRY-box transcription factor 9)
Diseases named in the same sentence as SOX9 in open-access papers (continued):
Sharing a sentence is not in itself a finding about the gene and the disease.
tumor (continued). "In addition, IHC showed that the expression of HPC markers (CK7, CK19, SOX9 and CD133) was higher in the tumour formed by HNF-1β overexpression HCC cells than the control group." (PMID 28684878, 2017). "In contrast to Sox2, the Sox9+ cells were not concentrated next to certain areas of the tumour, but rather widely distributed among all the adjoining brain parenchyma." (PMID 29158570, 2017). "We hypothesized that the elevated SOX9 expression in cancer cells and SWCNT-exposed cells may induce CSC formation, which in turn could drive tumor formation and metastasis." (PMID 28912540, 2017). "By qPCR we assessed the transcript levels of Sox9 in the tumor tissues and the corresponding non-tumorous liver tissues in 69 human HCC samples." (PMID 27105493, 2016). "Given that SOX2 and SOX9 H-scores were not that different between basal and suprabasal layers, for P-S6, we only scored the fraction of tumor cells that stained positive." (PMID 27880766, 2016). "Quantification of the bioluminescence signals showed variations in the tumor size of control mice (n = 8), but clearly evidenced an absence of detectable tumor upon induction of SOX9 expression (n = 8) as early as 4 days and up to 17 days post S9-CT26 graft." (PMID 27429045, 2016). "SOX9 has also been identified as a downstream target of ERG and a recent large histopathological study found a strong correlation between positive ERG status and moderate and high levels of SOX9 in PrCa tumor tissues." (PMID 27798103, 2016). "Because most SQCCs express high levels of SOX2 and low levels of SOX9 and show evidence of PI3K activity in at least some tumor cells (which could be stem cells), the mechanism we uncovered in stem cells may continue to promote squamous identity in SQCCs." (PMID 27880766, 2016). "Further studies comparing T2w-derived whole-body tumor burden, WB-MTV and WB-TLG will shed light on the usefulness of these techniques for providing an imaging biomarker correlating with known circulating biomarkers such as adrenomedullin, MIA or SOX9." (PMID 26625155, 2015). "In contrast, no unequivocal differences were found between SOX9 levels and tumor phenotype in ERG-negative cancers, although significant p-values were still obtained due to the very high number of samples in our study." (PMID 26030748, 2015). "SOX9, a high mobility group (HMG) box transcription factor, is highly up-regulated in many premalignant lesions and in tumor tissues and has been proposed to play an oncogenic role in tumor development." (PMID 26009899, 2015). "The combination of nanotechnology‐based PDT with siRNA‐mediated silencing of immune‐evasion molecules such as SOX9 enhances photosensitizer delivery efficiency and remodels the immune microenvironment, restoring DC and CD8+ T‐cell function and substantially improving tumor‐specific immune responses." (PMID 41270217, 2026). "Thus, SOX9 knockdown, in addition to reducing cell proliferation, can probably promote tumor cells to their death without involving caspases." (PMID 40141294, 2025). "Interestingly, Paneth cells are producers of antimicrobial peptides that interact with the gut microbiota and modulate immune cells, showing a contrasting pattern, being increased in tumor tissue, as indicated by the upregulation of the genes LYZ, DEFA1, SOX9, and WISP1." (PMID 41303610, 2025). "Additionally, lipid nanoparticles (LNPs) can deliver SOX9 siRNA to silence the SOX9 gene in cancer cells, thereby suppressing the anti-tumor immune response—particularly by impairing CD8+ T cell function—and ultimately inhibiting tumor growth." (PMID 41293317, 2025). "Thus, artificial suppression of SOX9 in PANC-1 cells decreased the number of cells carrying CD44 and CD24 markers, as well as decreased the ability of the cells to form spheres (sphere formation rate) and to initiate tumor in nude mice." (PMID 40141294, 2025).
tumor (continued). "Using HGSOC tumor data from The Cancer Genome Atlas and normal fallopian tube epithelium (FTE) expression data from the Genotype-Tissue Expression database in the UCSC Xena platform, we determined that SOX9 expression is much higher in HGSOC tissues than in normal FTE." (PMID 41031891, 2025). "Furthermore, we explore potential co-expression patterns or correlations between SOX9, GATA3, and GATA4, which may reflect shared regulatory pathways or converging roles in tumor differentiation, plasticity, or stromal remodeling." (PMID 41303462, 2025). "This suggested that the primary mechanism by which SOX9 improved patient outcomes might be independent of or only weakly related to the immune system, instead operating through direct effects on tumor cell-intrinsic biological behaviors." (PMID 40688093, 2025). "Thus, SOX9 promotes the recruitment of immunosuppressive MDSCs through chemokine regulation—particularly via CXCL5—thereby inhibiting effector lymphocytes and facilitating tumor immune escape." (PMID 41293317, 2025). "However, there was no significant tumor reduction in Akt-NRAS Sox9 iKO, with variable gross tumor presence and LW/BW ratios comparable to those of iWT mice." (PMID 39273023, 2024). "However, SOX9 cytoplasmic staining was neither observed at the tumor core nor at the invasive front of tumor samples of the HIPO-HNCC cohort, including OSCC." (PMID 38275880, 2024). "However, the entire Akt-YAP1 Sox9 LKO livers were full of circumscribed tumor foci which were negative or very weak for CK19." (PMID 39273023, 2024). "All of this could explain the inverse correlation between MEG8 and SOX9, since when MEG8 is overexpressed it shows a tumor suppressor role that could not be bypassed by the low levels of SOX9." (PMID 39706842, 2024). "There was great sensitivity and specificity with SGC, and the immunoreactivity pattern was nuclear and mostly located in basaloid cells of the tumor nest; this is similar to our sweat gland case, where palisading cells were readily positive for SOX9, while the mammary gland showed a negative result." (PMID 39765541, 2024). "As Sox9 transcripts were not altered compared to WT, this suggested post-transcriptional and/or post-translational mechanisms may limit SOX9 levels in these tumours." (PMID 37564373, 2023). "Interestingly, tumor nodules that failed to induce the IC gene program in response to Treg cell depletion expressed Sox9 in agreement with a recent study where upregulation of Sox9 in human LuAd conferred resistance to NK cells." (PMID 37127830, 2023). "The knockdown of SOX9 by siRNA treatment in a TNBC cell line induced TNBC cell death and reduced invasion by regulating gene expression involved in the cell death pathway including RIPK1 by Chip-seq analysis and reduced tumor growth and lung metastasis by SOX9 knockout in an in vivo animal model." (PMID 35159173, 2022). "Through establishing patient-derived cancer organoids, we found that stem cell-like cells (SOX9+ and MKI67+) may be the main component of tumor epithelial cells in vivo and that these cells can be self-renewal and further differentiate into other mature cell types." (PMID 35974387, 2022). "Furthermore, we evaluated expression of GRK3, YAP1, and SOX9 and cell proliferation marker Ki67 in the tumor tissues of mice treated with or without LD2 using IF." (PMID 35996148, 2022). "However, SOX9 staining was discovered to be almost absent in K14-HPV8-CER tumours, which is in line with the gene expression values." (PMID 35406439, 2022). "Moreover, the translocation pattern was categorized using “site-index”, and the results demonstrated that the overexpression of HMGB1 and SOX9 was mostly observed in both the nucleus and cytoplasm, whereas YAP1 was predominantly expressed in the cytoplasm of tumor cells." (PMID 35201494, 2021).
tumor (continued). "Data showing that DLL1+ BC tumor cells display CSC characteristics, together with our findings showing that DLL1 controls the expression of SOX9, supports the importance of these studies, which may provide additional insights into the mechanisms underlying DLL1’s key oncogenic role in BC." (PMID 34439228, 2021). "Immunostaining for CK19 and Sox9, common markers for expanded HPCs, was negative in the tumor." (PMID 32382012, 2020). "In extensive studies of murine neural developmental pathways and their potential role in human gliomagenesis, SOX9-dependent activation of the transcription factor nuclear factor I-A (NFIA) was shown to antagonise SOX10 function and result in astrocytic differentiation of the tumour cells." (PMID 33339831, 2020). "Also, in SOX9 expressing PCa cells, Wnt synthesis inhibitor (LGK974) could reduce Wnt signaling in vitro and growth of tumor in murine xenograft models." (PMID 31027362, 2019). "Consistent with this, in ER-positive tumour cells, Sox9 does not co-localise with ER." (PMID 30622340, 2019). "Finally, loss of Notch1 in tumor cells did not affect the protein expression of Notch2, Jag1, and BEC marker Sox9 as well as mRNA levels of Notch targets, including Hes5 and Hey2." (PMID 29545603, 2018). "However, data about the expression of Sox2 and Sox9 in the tumour surrounding brain tissue is lacking." (PMID 29158570, 2017). "Sox9 upregulation (tumor/non-tumor ≥ 4) was observed in 32 cases (46.4%)." (PMID 27105493, 2016). "Moreover, the level of SOX9 expression was shown to be very low in CT26 cells in comparison with normal BALB/c mice intestine and DLD-1 cells, which argued in favor of rather using this model to evaluate the incidence of SOX9 expression on tumor development." (PMID 27429045, 2016). "Therefore, we concluded that SOX9 induces the expression of S100P, which consequently activates its direct target, RAGE, and phosphorylates ERK1/2, subsequently leading to EMT, which promotes tumor invasion and metastasis." (PMID 26009899, 2015). "Moreover, since progression to high-grade disease was paralleled by a reduction of SOX9 expression in ERG-positive cancers, very strong SOX9 overexpression may even counteract tumor growth." (PMID 26030748, 2015). "Since the worst prognosis was found for PTEN-deleted and ERG-positive tumors that completely lacked any detectably SOX9 expression, SOX9 might even impair tumor growth in this specific molecular background." (PMID 26030748, 2015). "Therefore, it seems that SOX9 and c-myc might play more dominant roles than ERBB2 and WNT3 in determining tumor stemness in this tumor model." (PMID 25003837, 2014). "Additionally, in colorectal cancer, SOX9 activates the canonical Wnt/β-catenin pathway by promoting β-catenin stability, nuclear translocation, and transcription of Wnt components like FZD7 and LRP6, which drives tumor growth, metastasis, and stem cell-like properties." (PMID 41268614, 2026). "Patients with a strong SOX9 intensity score exhibited poor or moderate differentiation, longer tumor sizes, higher rates of perineural and vascular invasion, and a greater presence of lymph nodes and distant metastases compared to those with a non-strong SOX-9 intensity score (all, P < 0.05)." (PMID 39907598, 2025). "Additionally, we observed another interesting phenomenon: in the SOX9-positive group, the regions with the highest activation values were often located in the tumor and in peritumoral areas, whereas in the SOX9-negative group, the activated regions were limited to the tumor alone." (PMID 40428248, 2025). "Additionally, AN, but not AY, tumor formation partially depends on the Sox9-Dnmt1 cascade." (PMID 39273023, 2024).
tumor (continued). "Tumour cells featured some characteristics of adult Sertoli cells but lacked consistent SOX9 expression and exhibited an enhanced steroidogenic phenotype, which could arise from maintenance or acquisition of a fetal cell identity or acquisition of another somatic phenotype." (PMID 37564373, 2023). "Notably, we found that the ductal cell markers and epithelial cell-specific markers reported previously, such as EPCAM, KRT18, SOX9, KRT19, MUC1, and FXYD3, were commonly expressed in the majority of clusters except for cluster 17, confirming tumor cell identity." (PMID 37324492, 2023). "To assess whether the CXCR4 positive cells have the features of the tumor-initiating cells, we compared the mRNA expression levels of stemness-associated markers such as NANOG, OCT4, LIN28, and SOX9 between CXCR4 positive and negative cells by quantitative real-time PCR." (PMID 32232002, 2020). "Moreover, in NSCLC tumor tissues and cell lines (A549, H1299, HCC827, and H358), SOX9 could activate MALAT1 expression by binding MALAT1 promoter on a specific site (5′-TCATTGTGT-3′), thus creating a positive feedback loop which dramatically increases MALAT1 downstream effects." (PMID 32438606, 2020). "Besides, it is still not clear whether SOX9 anti-tumor activity in the intestine is mainly due to its conventional transcription factor activity or to its ability to directly inhibit the Wnt/ß-catenin signaling pathway." (PMID 27429045, 2016). "It is, thus, tempting to speculate that strong SOX9 overexpression inhibits progression through forced differentiation, and that ERG-positive cancer cells consequently need to undergo adaptation steps to adjust SOX9 expression to a level that is compatible with tumor progression." (PMID 26030748, 2015). "Interestingly, some SOX members (e.g. SOX21 and SOX9) have also been implicated in non-canonical Wnt signaling due to their modulation of planar cell polarity signaling (PCP), which is known to contribute to tumor progression and metastasis." (PMID 25594027, 2014). "Analysis of TCGA-LIHC data revealed elevated expression of SOX9, DCN, GPC3, and B3GNT3 in tumor tissues versus non-tumor counterparts." (PMID 41268541, 2025). "Specifically, gene expression did not vary significantly with gender (SOX9: p = 0.25; GATA3: p = 0.69; GATA4: p = 0.45), age group (<60 vs. ≥60 years; p range = 0.29–0.87), or tumor site (trunk vs. extremities; p range = 0.38–0.90)." (PMID 41303462, 2025). "LncRNA SOX9 antisense RNA 1 exerts multifaceted effects, not just controlling SOX9 expression but also encouraging EMT by altering the Wnt/β-catenin pathway, which speeds up the tumor cells’ malignant development." (PMID 40699663, 2025). "Again, transfection with miR-637 inhibitor failed to increase the number of tumor spheres and up-regulate the expression of stemness-related genes (SOX4, SOX9, Nanog, CD44 and ABCG2) after stable knockdown of WASH in KYSE70 cells." (PMID 36329557, 2022). "The tumor cells showed positive staining for the expression of pan-cytokeratin (AE1/AE3), S-100, brachyury, and SOX9 but negative staining for the expression of calretinin, D2-40, KIT, CD34, DOG-1, desmin, alpha-SMA, Melan-A, HMB45, and SOX10." (PMID 35398781, 2022). "Intriguingly, these studies rarely take into consideration the fact that SOX9 is a key transcription factor in developmental/non-neoplastic EMT processes, as well as in neoplastic disease." (PMID 34568045, 2021). "Tumor development was only observed in Sox9-Pten mice fed on DDC diet (100%, 5 out of 5) whereas none of the Sox9-Pten mice fed on NC developed any tumors at this age (0%, 0 out of 8)." (PMID 34083580, 2021). "These levels of SOX9 expression are able to trigger p21 but not sufficient to induce NEDD9 expression, resulting in suppression of tumor growth and metastasis." (PMID 30642390, 2019).
tumor (continued). "However, the narrow spreads in the majority of SOX2, SOX9, and P-S6 expression data may have limited the power of our statistical analyses, and histological tumor grade might not have been sensitive enough to detect differences in the extent of squamous differentiation." (PMID 27880766, 2016). "The expression of CD15, SOX2, SOX9, YKL40 and the proliferation marker Ki67 tended to be higher in cells derived from tumor core compared to UA cells, but the difference was not statistically significant." (PMID 27605047, 2016). "Heatmap analysis of gene expression in adherent cells and stem‐like tumor spheres revealed a negative correlation between YY2 and stem‐related factors, including CD44, SOX9, SALL2, KLF15, OCT4 (also known as POU class 5 homeobox 1 or POU5F1), MYC, ASCL1, and POU3F2." (PMID 37300334, 2023). "Simultaneous SOX9 overexpression does not affect IPMN incidence, but reduces PDAC formation, demonstrating that Sox9 is a major downstream target of Arid1a and prevents tumor progression by promoting ductal differentiation." (PMID 34888306, 2021). "Compared to the in vivo situation, we could not identify two clearly distinct SOX9+ and OLIG1+ tumoral cells in these cultures, and the majority of cells coexpressed OLIG1 and SOX9 (Lane 4)." (PMID 33925547, 2021). "Also, we discovered the expression of SOX9 in in vivo tumours was not affected by PXN‐AS1 inhibition, suggesting SOX9 was the upstream of PXN‐AS1 in GBM." (PMID 32329150, 2020). "The tumor cells are immunostain positive for INSM1, SOX9, CD99 and S100, but negative for MUC4." (PMID 32164724, 2020). "The inclusion of deletion data from multiple chromosomal loci revealed further, that the relationship of SOX9 and ERG expression largely depended on whether or not a PTEN deletion was present in a tumor." (PMID 26030748, 2015). "However, Dnmt1 re-expression in Sox9 CKO livers slightly but significantly restored tumor formation driven by Akt-NRAS, but not Akt-YAP1, implying the partial involvement of Dnmt1 in Akt-NRAS tumor development under the SOX9." (PMID 39273023, 2024). "Indeed, immunostaining in KJC mice found that ductal cells lining SCN-like lesions were completely negative for Sox9, and IPMN-like lesions showed no or very weak Sox9 staining, whereas a rarely formed PDAC showed clear nuclear staining of Sox9 in ductal tumor cells." (PMID 33268505, 2021).